RNF43 (ring finger protein 43)
Diseases named in the same sentence as RNF43 in open-access papers (continued):
Sharing a sentence is not in itself a finding about the gene and the disease.
endometrial cancer (21 papers, 2015 to 2025). Primary or metastatic malignant neoplasm involving the endometrium (mucous membrane that lines the endometrial cavity). "Mutations in RNF43, identified in blood samples from colon, ovary, pancreas, stomach, and endometrial cancer patients, provide an informative guideline for the selection of a patient population that will positively respond to a given drug." (PMID 39125653, 2024). "In both CRC and endometrial cancer, a hotspot mutation at G659 induces a frameshift, leading to a truncated form of RNF43." (PMID 37048063, 2023). "RNF43 encodes an E3 ubiquitin ligase that negatively regulates Wnt signaling, and it is mutated in more than 18% of colorectal adenocarcinomas and endometrial carcinomas." (PMID 36831448, 2023). "To demonstrate the eVIP2 software and approach, we characterized two recurrent frameshift variants in RNF43, a negative regulator of Wnt signaling, frequently mutated in colorectal, gastric, and endometrial cancer." (PMID 34214079, 2021). "Over 18% of colorectal adenocarcinomas and endometrial carcinomas have RNF43 mutations with p.G659Vfs*41 and p.R117Afs*41 being the most common." (PMID 34214079, 2021). "Somatic mutations of RNF43 in 14% to 19% of colorectal, pancreatic, and endometrial cancers were recently reported." (PMID 29293510, 2018). "All these observations led to a seemingly obvious conclusion that nonsense and frameshift RNF43 mutations are loss-of-function mutations that would lead to tumorigenesis in a significant subset of gastrointestinal and endometrial cancers due to increased Wnt signaling." (PMID 31811196, 2019). "Recently, a study reports that RNF43 is frequently mutated in colorectal and endometrial cancers." (PMID 27556693, 2016). "Patients with endometrial cancer also had high prevalence of variants in PTEN (52.0%), CTNNB1 (15.6%), and RNF43 (10.5%) genes." (PMID 39277826, 2024). "Frequent mutations of RNF43 has been reported in sporadic CRC, endometrial cancer, gastric adenocarcinoma, and intraductal papillary mucinous neoplasms of the pancreas." (PMID 29416670, 2018). "In addition, our results showed that patients with endometrial carcinoma, esophagogastric adenocarcinoma, and colorectal adenocarcinoma had the top highest frequency of RNF43 alterations." (PMID 37848933, 2023). "Other interesting findings from the NGTS were: (i) frequent detection of RNF43 mutations in both dVIN and de-VIL, which have been previously associated with endometrial carcinoma, and (ii) detection of mutations in KEAP1, CDH1, PIK3R1, and POLE exclusively in de-VIL." (PMID 33918187, 2021). "It was only recently shown that RNF43 is frequently mutated in CRC and endometrial cancers." (PMID 25853550, 2015). "However, in stomach and endometrial cancers, expression of RNF43 in G659Vfs*41 or non-G659Vfs*41 tumors was not different from those without any RNF43 mutation." (PMID 31811196, 2019).
ovarian carcinoma (12 papers, 2012 to 2024). A malignant neoplasm originating from the surface ovarian epithelium. "Inactivating RNF43 mutations in blood samples of ovarian cancer patients were detected, leading consequently to high Wnt signaling and stabilization of β-catenin." (PMID 38275417, 2024). "Inactivating endogenous mutations in RNF43 have been found in tumors of the gastrointestinal (GI) system and endometrial and ovarian cancer." (PMID 39125653, 2024). "We describe a multi-generation CRC-affected family segregating pathogenic variants in both BRCA1, a gene associated with breast and ovarian cancer and RNF43, a gene associated with Serrated Polyposis Syndrome (SPS)." (PMID 38063999, 2024). "On the other hand, inactivating RNF43 mutations, found in several types of cancer including cancers of the gastrointestinal (GI) system, endometrium, and in ovarian cancer, lead to high β-catenin levels and increased FZD levels." (PMID 38275417, 2024). "It is important to evaluate the impact of these RNF43 mutations on levels of PAR2 in ovarian cancer." (PMID 38275417, 2024). "Regarding the tumorigenesis of pancreatic and ovarian cancers, inactivating mutations in RNF43 are supposed to abrogate Wnt signaling including canonical and non-canonical pathways." (PMID 24466159, 2014). "RNF43 mutations with impaired E3 ligase activity were found in several types of cancers (e.g., gastrointestinal system tumors and endometrial and ovarian cancer), pointing to a high dependency on FZD receptors and possibly PAR2 and the PI3K/AKT/mTOR signaling pathway." (PMID 39125653, 2024). "The E3 ubiquitin ligase RNF43 can induce FZD ubiquitination and lysosomal degradation to negatively regulate the Wnt pathway, but RNF43 mutations are found in ovarian cancer, and its mutation frequency is second only to KRAS in mucinous ovarian cancer." (PMID 39253578, 2024). "The average expression levels of DLG3 in breast, kidney, liver, lung, and ovarian cancers, and RNF43 in colon, liver, lung, ovarian, and prostate cancers were also found to be higher than their normal tissues." (PMID 23282184, 2012).
colorectal tumors (11 papers, 2017 to 2026). "Frameshift RNF43 mutations involving mononucleotide repeats are often observed in colorectal tumors with MMR deficiency." (PMID 36734304, 2023). "Colorectal tumors with mutated RNF43/ZNRF3 or R-spondins 2/3 are sensitive to abrogation of Wnt secretion." (PMID 34849464, 2021). "ZNRF3 is a homolog of RNF43 but truncating mutations are rare in colorectal tumors, potentially reflecting its comparably low mRNA expression in normal colon and colorectal tumors." (PMID 33202731, 2020). "RNF43 was mutated in approximately 80% of microsatellite instability colorectal tumors and 4.8% of microsatellite stable (MSS) tumors." (PMID 29293510, 2018). "Prior to further filtering and validation steps of the exome sequencing data, we looked for variants in 123 genes including RNF43 and other driver candidate genes of the serrated pathway and established causative genes or candidate genes for (hereditary) colorectal tumours." (PMID 29213343, 2017). "Approximately 15% of colorectal tumors have ligand-dependent alterations in the Wnt signaling pathway, affecting RNF43 or RSPO2/3." (PMID 33202731, 2020). "Wnt signaling is ubiquitously activated in colorectal tumors and driver mutations are identified in genes such as APC, CTNNB1, RNF43 and R-spondin (RSPO2/3)." (PMID 33202731, 2020). "Our results provide an underlying mechanism for a recent study in which the authors reported that FZD5, but not the other FZDs, is crucial for the growth of RNF43-mutated pancreatic tumors and colorectal tumor organoids." (PMID 39463927, 2025). "Additionally, we found a heterozygous nonsense mutation in APC and frameshift indels in known colorectal tumor suppressors; ATM, SOX9, RNF43, and ZFP36L2, of likely driver status." (PMID 32697969, 2020). "Additionally, we found that the RNF43 G659Vfs*41 mutant, a hotspot frameshift mutation in human colorectal tumors that may not potentiate WNT signaling, elevates EGFR protein levels, suggesting that this mutation may exert its oncogenic role in cancer through EGFR upregulation." (PMID 38260423, 2024). "Thus, we could not complete the analyses for the prognosis of colorectal tumour patients to clarify the roles of RNF43 phospho-regulation in tumorigenesis due to an insufficient numbers of samples." (PMID 32934222, 2020).
pancreatic adenocarcinoma (11 papers, 2019 to 2024). "Of note, we also found B7-H3–high pancreatic adenocarcinomas to display fewer inactivating mutations in RNF43, which has recently been shown to accelerate the progression of KRAS-driven pancreatic neoplasia." (PMID 38709075, 2024). "RNF43 inactivating variants have been reported in several gastro-entero-pancreatic neoplasms, including colon adenocarcinoma, pancreatic adenocarcinoma, and intraductal papillary mucinous neoplasms of the pancreas." (PMID 35075588, 2022). "RNF43 encodes a ubiquitin ligase that downregulates Wnt signaling activity in pancreatic adenocarcinoma cells." (PMID 32894083, 2020). "Moreover, RNF43 is recurrently mutated in several cancer types, and RNF43 mutations can promote the initiation and development of human malignancies, such as gastrointestinal cancers, hepatocellular carcinoma, and pancreatic adenocarcinoma." (PMID 37848933, 2023). "In pancreatic adenocarcinoma, the RNF43 F69C mutation is associated with a significantly reduced expression of FZD compared to wild-type cells, highlighting the importance of RNF43 in pancreatic adenocarcinoma development." (PMID 38886806, 2024). "Treatment of RNF43 mutant pancreatic adenocarcinoma cell line HPAF-II with LGK974, a small molecule that inhibits all Wnt secretion, led to cell cycle arrest and potent inhibition of proliferation." (PMID 31452509, 2019). "We showed that, in coculture with human PBMCs, control RNF43-mutant HPAF-II pancreatic adenocarcinoma cells inhibit the stimulation of GMCSF and IFNγ production as well as CD4 and CD8 T-cell proliferation, effects that were reversed by preincubation of the HPAF-II cells with RXC004." (PMID 36922934, 2022). "The level of RNF43 was increased in gastric, colon and pancreatic adenocarcinoma." (PMID 32764696, 2020). "For example, genome-scale pooled CRISPR screening technology was applied to identify vulnerabilities in RNF43(ring finger protein-43)-mutant pancreatic adenocarcinomas, finding FZD5 (frizzled class receptor 5) as a common vulnerability that can be exploited therapeutically." (PMID 31947935, 2020).
pancreatic ductal adenocarcinoma (11 papers, 2014 to 2024). An infiltrating adenocarcinoma that arises from the epithelial cells of the pancreas. "Previous studies have used genome-wide CRISPR/Cas9 to screen pancreatic ductal adenocarcinoma cells with RNF43 mutations." (PMID 37749638, 2023). "By constructing a genetically engineered pancreatic ductal adenocarcinoma mouse model via conditional expression of oncogenic Kras and deletion of the catalytic domain of RNF43, loss of RNF43 promotes pancreatic ductal adenocarcinoma tumorigenesis, and contributes to decreased survival time of mice." (PMID 37848933, 2023). "Moreover, in comparison with OMP-18R5 and OMP-54F28, F2.A demonstrates superior efficacy in treating RNF43-mutant pancreatic ductal adenocarcinoma." (PMID 38886806, 2024). "Furthermore, knockout of FZD-5 robustly inhibited cell growth in breast cancer cells and RNF43-mutant pancreatic ductal adenocarcinoma cells." (PMID 33723319, 2021). "Knockout of FZD5 robustly inhibited cell growth in human Ring finger protein 43 (RNF43)-mutant pancreatic ductal adenocarcinoma cells (PDAC) in clonogenic growth assays, and editing of FZD5 significantly inhibited the expression of WNT target genes AXIN2 and NKD1(Naked cuticle homolog 1)." (PMID 29789460, 2018). "It is possible that mRNA overexpression of CK1γ3 in cancer may yield a WNT hyper-responsive cell state, not unlike RNF43 mutations and WNT addiction in pancreatic ductal adenocarcinoma." (PMID 35487243, 2022).
breast cancer (9 papers, 2019 to 2025). A primary or metastatic malignant neoplasm involving the breast. "Subclonal diversity and dynamics were evident across all cases with potential therapy resistant subclones detected containing known HER2+ breast cancer driver genes such as AURKA or novel candidate mutations such as RNF43 for future studies." (PMID 37758711, 2023). "The only other cancer type with G659Vfs*41 mutation being identified more than once is breast cancer (3/16 RNF43 mutations in 1066 cases)." (PMID 31811196, 2019). "Together, these findings indicate that RCOR2 enhances Wnt/β-catenin activation by RNF43 silencing, leading to increased breast cancer plasticity." (PMID 40608411, 2025). "We show a partial rescue effect of RNF43 silencing or CHIR99021 treatment on stemness of RCOR2-null breast cancer cells, although β-catenin activity is fully restored by these two interventions." (PMID 40608411, 2025). "A strongly positive expression of RNF43 was observed in kidney renal clear cell carcinoma, lung cancer, and breast cancer." (PMID 37848933, 2023). "The expression of RNF43 was further validated by IHC among 4 different types of cancer by our cohorts, including breast cancer, lung cancer, kidney renal clear cell carcinoma, and sarcoma." (PMID 37848933, 2023). "Further testing of alpelisib, which is FDA-approved for breast cancer treatment, and PF-04691502, currently in clinical trials, showed selective killing of CRC organoids harboring the RNF43_p.G659Vfs mutation." (PMID 35676246, 2022). "RNF43 silencing by the RCOR2-LSD1 axis is responsible for maintenance of breast cancer stemness." (PMID 40608411, 2025). "Besides, immunohistochemistry (IHC) was employed to validate the expression of the RNF43 in different cancer types by our clinical cohorts, including patients with lung cancer, sarcoma, breast cancer, and kidney renal clear cell carcinoma." (PMID 37848933, 2023). "To further confirm that activation of Wnt/β-catenin signaling is responsible for RCOR2-induced breast cancer cell plasticity, we treated RCOR2-KO1 MDA-MB-231 cells with a specific GSK3 inhibitor, CHIR99021 (1 μM), which can bypass RNF43 to activate β-catenin." (PMID 40608411, 2025). "In MDA-MB-231, a breast cancer cell line with moderate levels of ZNRF3/RNF43, overexpression of either ZNRF3 or RNF43 substantially reduced EGFR protein levels." (PMID 38260423, 2024).
colorectal adenocarcinoma (9 papers, 2018 to 2025). The most common type of colorectal carcinoma. "Consistently, in the TCGA Colorectal Adenocarcinoma dataset (n = 500 CRCs), the mRNA expression of interferon pathway genes were significantly lower in the samples with RNF43_p.G659fs mutation than those with wildtype RNF43." (PMID 35676246, 2022). "LURE analysis found RNF43 truncating mutations to have similar transcriptional signatures to BRAF mutations in colorectal adenocarcinomas." (PMID 34214079, 2021). "We further investigated the evidence of RNF43 truncating mutations being associated with MAPK/RTK pathway activation in primary colorectal adenocarcinoma by incorporating the more expansive RNF43 mutation calls identified with manual review from Giannakis et." (PMID 34214079, 2021). "Truncating mutations of RNF43 are more prevalent in MSI tumors and show mutual exclusivity with inactivating APC mutations in colorectal adenocarcinomas." (PMID 40757636, 2025). "The mutually exclusive alterations in APC and RNF43 has been reported in microsatellite-unstable colorectal adenocarcinomas." (PMID 39011117, 2024). "The LURE analysis of colorectal adenocarcinoma patient samples is consistent with MAPK/ERK and MAPK/JNK being the most activated pathways in both RNF43 R117fs and RNF43 G659fs in the reporter assays." (PMID 34214079, 2021). "For example, a novel association was detected between mutations in two different modulators of the Wnt signaling pathway (RNF-43 and DOCK3) and increased CD8+ T cell infiltration in colorectal adenocarcinoma (COAD)." (PMID 30622534, 2018).
colon adenocarcinoma (8 papers, 2018 to 2024). "In many RNF43 frameshift mutant TCGA colon adenocarcinoma patient samples, we found activation of EMT, NFKB, and hypoxia marker genes." (PMID 34214079, 2021). "COAD (Colon Adenocarcinoma) is enriched with B2M, PTEN, and RNF43 double mutations." (PMID 36808143, 2023). "For example, loss of function mutations in RNF43 and DOCK-3 genes were associated with higher infiltration of CD8+ T cells in colon adenocarcinoma (COAD)." (PMID 30622534, 2018). "RNF43 was highly expressed in rectum adenocarcinoma (READ), and colon adenocarcinoma (COAD), whereas was lowly expressed in lymphoid neoplasm diffuse large B-cell lymphoma (DLBC), glioblastoma (GBM) and sarcoma (SARC)." (PMID 37848933, 2023).
hepatocellular carcinoma (7 papers, 2016 to 2025). A malignant tumor that arises from hepatocytes. "RNF43 gene has been functionally characterized in multiple cancers such as pancreatic, gastric and hepatocellular carcinoma." (PMID 36866106, 2022). "RNF43 can promote the growth, proliferation and invasion of cancer cells in hepatocellular carcinoma." (PMID 36497451, 2022). "In human hepatocellular carcinoma (HHC), RNF43 overexpression frequently occurred and study had shown correlated with RNF43 expression and vascular invasion." (PMID 35180847, 2022).
prostate carcinoma (7 papers, 2012 to 2024). A carcinoma that arises from epithelial cells of the prostate gland. "Prostate cancer is the most common non-cutaneous cancer in men worldwide, and multiple studies have detected RNF43 mutations in prostate cancer." (PMID 37848933, 2023). "In prostate cancer, RNF43 genetic mutations are present in primary and metastatic disease (≤1% and 1.8–2.5%, respectively), with around half of the variants occurring in the C-terminus." (PMID 35204808, 2022). "Copy number loss of 17q22 is correlated with lower RNF43 and SRSF1 expression, enzalutamide resistance, and poor prognosis in prostate cancer." (PMID 37848933, 2023). "In human prostate cancer, PTEN loss is an early tumorigenic lesion, while Wnt-pathway activation through aberrations in APC, CTNNB1, RNF43, and RSPO2 are found in metastatic castration-resistant cancer, suggesting they are associated with tumor progression." (PMID 27536883, 2016). "Of interest, majority of gene loci identified have been reported to be aberrant in prostate cancer biology, such as copy number changes after treatment in RNF43 and ZNRF3 loci." (PMID 27127882, 2016). "Using cBioPortal, we also detected a negative correlation between ZNRF3/RNF43 expression and EGFR protein in multiple other cancer types, including prostate cancer where ZNRF3 or RNF43 is deleted or mutated with a rate of 5%." (PMID 38260423, 2024).
gastric tumor (6 papers, 2016 to 2024). "Considering the high prevalence of H. pylori infection and the increased incidence of RNF43 mutations detected in gastric tumors, further studies should be conducted to understand how both events interrelate." (PMID 30884828, 2019). "Whole exome and whole genome sequencing studies reported RNF43 to be frequently mutated in gastric tumors." (PMID 30884828, 2019). "In this context, the E3 ubiquitin ligase ring finger protein 43 (RNF43) was found to be frequently mutated in gastric tumors highlighting an important role for RNF43 in gastric carcinogenesis." (PMID 30884828, 2019). "In addition, RNF43 downregulation in gastric tumors was associated with metastasis, TNM staging and poor survival, suggesting that loss of RNF43 function is one of the key events in gastric carcinogenesis." (PMID 30884828, 2019).
intraductal papillary mucinous neoplasms (6 papers, 2016 to 2022). "The initial report of RNF43 mutations was in benign pancreatic tumors called intraductal papillary mucinous neoplasm (IPMN) and mucinous cystic neoplasm (MCN)." (PMID 27338477, 2016). "The prevalence and clinical significances of KRAS, GNAS, and RNF43 mutations in patients with pancreatic intraductal papillary mucinous neoplasm (IPMN) remain elusive." (PMID 27512631, 2016). "This pooled analysis using data from 1253, 835, and 143 pancreatic IPMN patients revealed that overall KRAS, GNAS, and RNF43 mutations were detected in 61, 56, and 23 %, respectively." (PMID 27512631, 2016). "The Wnt/β‐catenin signaling pathway was activated in pancreatic KrasG12D and Rnf43 knockout mice and the PORCN inhibitor LGK974 blocked pancreatic IPMN initiation and progression to PDAC accordingly." (PMID 35229994, 2022).